HDAC1 (histone deacetylase 1)
Diseases named in the same sentence as HDAC1 in open-access papers (continued):
Sharing a sentence is not in itself a finding about the gene and the disease.
hepatocellular carcinoma (51 papers, 2012 to 2025). A malignant tumor that arises from hepatocytes. "NNT deficiency was reported to decrease HDAC1 activity and increase global protein acetylation in hepatoma cells." (PMID 35626691, 2022). "HDAC1 is a widely investigated member of the class I HDACs family, and it is implicated in the development of gastric, pancreatic, and hepatocellular cancers." (PMID 25629315, 2015). "In hepatocellular carcinoma, high HDAC1 expression was associated with cancer cell invasion into the portal vein, poor histological differentiation and low patient survival." (PMID 22496786, 2012). "In support of this theory, it has been shown that mouse hepatoma Hepa-1c1c7 (Hepa-1) cells treated with chromate caused the cross-linking of DNMT1 with HDAC1, which resulted in reduced methylation activity; this may be attributed to Cr(III) formed upon the intracellular reduction of Cr(VI)." (PMID 39337613, 2024). "We have previously shown that HDAC1, HDAC2, and HDAC3 (HDAC1–3) genes encoding histone deacetylases 1–3 are upregulated in primary human hepatocellular carcinoma (HCC)." (PMID 27342975, 2016). "In hepatocellular carcinoma, the majority of lactylation sites exhibit positive correlations with HDAC1-3, and knockdown of HDAC3 in HepG2 cells leads to an increase in lactylation intensity." (PMID 38711083, 2024). "HDAC1 has been reported to be overexpressed in hepatocellular carcinoma, and inhibition of HDAC1 induces autophagy to repress tumor cell growth." (PMID 33483607, 2021). "For instance, pterostilbene suppressed the growth and invasion of hepatocellular carcinoma through effectively inhibiting the levels of the MTA1/HDAC1/NuRD complex and promoting phosphatase and tensin homolog (PTEN) acetylation." (PMID 34924813, 2021). "HDAC1 has been proved to be closely related to the occurrence and development of hepatocellular carcinoma." (PMID 34616672, 2021). "Pterostilbene suppressed the growth and invasion of hepatocellular carcinoma through inhibiting the MTA1/HDAC1/NuRD complex and promoting PTEN acetylation." (PMID 34924813, 2021). "PLK1-mediated inhibition of PRC2 and KDM1A/CoREST/HDAC1 has been shown to stimulate the Wnt signaling pathway by increasing β-catenin expression and to promote the progression of hepatocellular carcinoma." (PMID 34361112, 2021). "HBV-associated chromatin modifying enzymes of PCAF, p300/CBP, HDAC1, SIRT1, and EZH2 have been shown to bind to the cccDNA in human hepatoma cells containing replicating HBV49." (PMID 30115977, 2018). "HDAC1 is highly expressed in hepatocellular carcinoma, breast, and liver, prostate, gastric and colon cancer; and HDAC2 is overexpressed in colorectal, cervical and gastric cancer." (PMID 26905733, 2016). "It is well known that HDAC1, a human homolog of Rpd3, is highly expressed in hepatocellular carcinoma." (PMID 27907135, 2016). "In the present study, VPA was demonstrated to be an HDACI, as HDAC activity and the HDAC1 gene expression of hepatocellular carcinoma cells was inhibited by it." (PMID 25621063, 2015). "Recently, HDAC1 has been reported to be overexpressed in hepatocellular carcinoma (HCC), but its biological roles in hepatocarcinogenesis remain to be elucidated." (PMID 22496786, 2012). "In addition, the O-GlcNAcylation of HDAC1 overexpressed in hepatocellular carcinoma (HCC) promotes cancer progression, thus inhibiting O-GlcNAcylation of HDAC1, repressing the progression of HCC." (PMID 36010594, 2022). "Importantly, we also found the co-localisation of MBD3 with CHD4 and HDAC1 in human hepatocellular carcinoma samples." (PMID 35501390, 2022). "In addition, HOXA10 silencing suppresses the proliferation of hepatoma cells, induces cell cycle arrest and apoptosis by upregulating HDAC1 transcription, which was consistent with our findings." (PMID 33596966, 2021). "HDAC1 also leads to PTEN deacetylation in hepatocellular carcinoma." (PMID 34925033, 2021).
hepatocellular carcinoma (continued). "A previous study showed that HBx could induce HDAC1 expression at the transcriptional level to enhance hypoxia signaling in hepatoma cells." (PMID 29316268, 2018). "mSin3A and HDAC1 are O-GlcNAcylated in HepG2 liver carcinoma cells." (PMID 29864144, 2018). "Firstly, it was found that, as an HDAC inhibitor, VPA could inhibit HDAC activity and HDAC1 gene expression in hepatocellular carcinoma cells and, as a result, an inhibition of cell proliferation was detected by MTT assay." (PMID 25621063, 2015). "A study in hepatocellular carcinoma (HCC) cells has indeed demonstrated that inhibition of HDAC1 and HDAC2 triggered increased expression of p21WAF1 and p19INK4D and subsequent growth arrest." (PMID 34253688, 2021). "HDAC1 is also required for TGFβ1-induced EMT in hepatocytes and frequently overexpressed in hepatocellular carcinoma (HCC), suggesting a strong connection between HDAC1 and the invasive properties of HCC." (PMID 26905733, 2016). "Here, we show that TPX2 is lactylated at K249 in hepatocellular carcinoma (HCC) tumour tissues and that this process is regulated by the lactylase CBP and the delactylase HDAC1." (PMID 40107714, 2025). "Epigenetically, YY1 can recruit HDAC1 to form a repressor complex that downregulates HOXD3 expression, thereby suppressing the ITGA2 pathway in hepatocellular carcinoma cells." (PMID 40940943, 2025). "In the present study, we sought to explore the biological importance of lysine lactylation in hepatocellular carcinoma (HCC) progression by regulating the function of cell cycle regulators and discovered that TPX2 is lactylated at K249 via CBP and HDAC1 in HCC cells." (PMID 40107714, 2025). "Moreover, evidence indicates that CXXC5 can facilitate the TGF-β signaling pathway in hepatocellular carcinoma (HCC) by interacting with HDAC1, and its overexpression was discovered to result in apoptosis and cell cycle arrest in HCC." (PMID 39806388, 2025). "Kcr expression was also downregulated in HCC, correlating with the TNM stage, while HDAC1 and HDAC3 simultaneous knockdown or HDACi trichostatin A (TSA) treatment improved the Kcr level, coincidently limiting hepatoma cell motility and proliferation." (PMID 38315203, 2024). "After univariate cox regression analysis, lasso analysis and multivariate cox analysis, a five-gene signature (including HDAC1, BIRC5, SPP1, STC2, NR6A1) was constructed to predict the prognosis of hepatocellular carcinoma." (PMID 34616672, 2021). "The results of immunohistochemistry showed that the protein expression levels of HDAC1, BIRC5, SPP1, STC2 in hepatocellular carcinoma tissues were higher than those in normal tissues." (PMID 34616672, 2021). "Previous studies have indeed demonstrated the involvement of p19INK4D in proliferative arrest after HDAC1 and HDAC2 inhibition in hepatocellular carcinoma cells, as well as the involvement of p15INK4B after treatment of HaCat cells with TSA or NaB." (PMID 34253688, 2021). "FK228, which is a specific HDAC1 and HDAC2 inhibitor, was confirmed to induce cell cycle arrest in the G1/S phase in hepatocellular carcinoma." (PMID 31993801, 2020). "Depletion of HDAC1 and HDAC2 increased cell death and inhibited cell viability in hepatocellular cancer cell lines." (PMID 29945926, 2018). "In hepatocellular carcinoma (HCC) cells, O-GlcNAcylation of HDAC1 at Thr114 and Ser263 in turn promotes its phosphorylation, thereby further impacts its deacetyltransferase activity." (PMID 30082668, 2018). "Previous studies have shown that HDAC1 and HDAC2 are frequently overexpressed in hepatocellular carcinoma and that higher expression levels are associated with poorer survival, suggesting their potential value as prognostic biomarkers and therapeutic targets in HCC." (PMID 41458606, 2025).
hepatocellular carcinoma (continued). "Recent pharmacological study using santacruzamate A, in combination with other HDAC inhibitors, such as HDAC1 inhibitor, tacedinaline, HDAC1/2 common inhibitor, romidepsin (FK228) and global HDAC inhibitor, vorinostat (SAHA), to treat hepatocellular carcinoma (HCC) was reported." (PMID 32397127, 2020). "Hepatitis B virus X protein, a viral oncoprotein from hepatitis B virus, may induce histone deacetylase 1 (HDAC1) expression and enhance hypoxia signaling in hepatocellular carcinoma cells." (PMID 24304587, 2013). "Using the same approach, several cellular transcription factors (CREB, ATF, YY1, STAT1, and STAT2) and chromatin modifying enzymes (PCAF, p300/CBP, HDAC1, SIRT1, and EZH2) have been shown to bind to the cccDNA in human hepatoma cells containing replicating HBV." (PMID 24133502, 2013). "In addition, during TGF-β-initiated EMT, the effect of TGF-β on Snail2 expression is related to the inhibition of HDAC1 and HDAC3, which can suppress Snail2 transcription by downregulating the acetylation levels of H3K56 and H3K4 in hepatocellular carcinoma (HCC) cells." (PMID 35484625, 2022).
ovarian carcinoma (47 papers, 2007 to 2024). A malignant neoplasm originating from the surface ovarian epithelium. "Increased expression of HDAC1, 2 and 3 has been associated with poor outcome in gastric and ovarian cancer, while high HDAC8 levels correlate with advanced disease and poor survival in neuroblastoma." (PMID 34654445, 2021). "A study on chemoresistant A2780-AD ovarian cancer cells of the molecular mechanisms of epigenetic modifications associated with HDAC1 overexpression showed the mediated HDAC1 suppression of the G-protein 10 signaling regulator (RGS10), which performs a key function in inflammation and cell survival." (PMID 37834214, 2023). "In another study, it was observed that HDAC1 was highly expressed in cisplatin-resistant ovarian cancer cells compared with a sensitive subline, also indicating reduced histone acetylation associated with cisplatin in ovarian cancer." (PMID 38256203, 2024). "For example, in cisplatin-resistant ovarian cancer cells, HDAC1 was highly expressed compared with cisplatin-sensitive cells and ovarian cancer xenografts." (PMID 38256203, 2024). "Silencing of HDAC1 in ovarian cancer cells was found to overcome resistance to cisplatin, and silencing of both HDAC1 and HDAC6 was found to enhance cytarabine-induced apoptosis of acute myeloid leukemia (AML) cells induced by cytarabine." (PMID 38004560, 2023). "The suppression of HDAC1 and DNA methyltransferase activity in platinum-resistant ovarian cancer cells restored cisplatin-mediated cell deaths through the upregulation of RGS10, an essential regulator of cell survival and chemoresistance." (PMID 36984544, 2023). "We found that PARP inhibitors Niraparib and Olaparib were unable to significantly promote HRD-EXCUTE signature, but the combination of PARPi and the selective HDAC1/3 inhibitor Entinostat further improved HRD-EXCUTE in ovarian cancer." (PMID 37063431, 2023). "Romidepsin, an HDAC1/2 selective inhibitor, is able to inhibit ovarian cancer metastasis through inhibiting the functions of CHD4 that are mediated by histone deacetylase." (PMID 37894746, 2023). "Histone deacetylase 1 is a predictor of an unfavorable tumor phenotype in gynecological cancers: ovarian carcinomas and cervical carcinomas." (PMID 37834214, 2023). "In ovarian cancer cells, the expression of HDAC1 and HDAC2 was significantly positively correlated with the expression of Ki-67, which is essential for the proliferation of ovarian cancer cells." (PMID 37894746, 2023). "In the meantime, reports have revealed that histone deacetylase 1 (HDAC1) plays vital roles in multiple cancers, such as laryngeal squamous cell carcinoma, ovarian cancer, and NSCLC." (PMID 35864549, 2022). "In ovarian cancer, HDAC1 promotes cancer cell proliferation by increasing cyclin A, and HDAC2 interferes with cisplatin-induced activation of DNA damage responses by remodeling chromatin." (PMID 36172179, 2022). "Knocking down of HDAC1 has been reported to enhance the sensitivity to cisplatin-based chemotherapy in ovarian cancer, indicating that HDAC1 is a potential therapeutic target." (PMID 35252174, 2022). "Among them, HDAC1 and HDAC2 are class I HDACs, whose increased expression is an independent risk factor for poor prognosis of malignant ovarian tumors." (PMID 36172179, 2022). "Similar to ovarian carcinomas, high-grade endometrial carcinomas express high levels of HDAC1, HDAC2 and HDAC3, while less aggressive subtypes show lower levels of HDAC expression." (PMID 33669182, 2021). "Drug-induced inactivation or gene silencing of HDAC1 suppressed ovarian cancer cell growth, and inhibition of HDAC1/2/3 using the inhibitor Panobinostat, slowed the growth of ovarian cancer in a xenograft mouse model." (PMID 33669182, 2021).
ovarian carcinoma (continued). "Importantly, HDAC1 levels increase over time following cell transformation in ovarian cancer, from an almost undetectable expression to a frank induction in malignant lesions, which is also associated with a poor prognosis, suggesting a role of HDAC1 as a diagnostic biomarker." (PMID 32183227, 2020). "A similar mechanism can be found in ovarian cancer, where HDAC3 epigenetically silences the expression of E-cadherin, stimulating cell migration and invasion, while HDAC1 and -2 are associated with increased cell proliferation and to platinum resistance." (PMID 32183227, 2020). "Inhibition of HDAC1 reduced c-Myc expression, increased miR-34a expression and sensitized ovarian cancer cells to cisplatin-induced apoptosis." (PMID 35582723, 2019). "In cisplatin-resistant ovarian cancer cells, they showed that HDAC1 knockdown suppressed cell proliferation and increased apoptosis." (PMID 35582723, 2019). "Role of HDAC1 in our finding coincides with previous study in which HDAC1 silencing in ovarian cancer enhances the chemotherapy response." (PMID 31358016, 2019). "Accordingly, miR-34a directly bound to HDAC1, and downregulated its expression, which subsequently decreased the resistance to cisplatin and suppressed proliferation in ovarian cancer cells." (PMID 35582723, 2019). "We talked about the association between endometriosis and ovarian cancer, such as HDAC gene expression and the increase of proteins of both HDAC1 and HDAC2 in endometriosis and ovarian cancer." (PMID 29780815, 2018). "We identify two important epigenetic regulators, HDAC1 and DNMT1, that exhibit aberrant association with RGS10 promoters in chemoresistant ovarian cancer cells." (PMID 24475290, 2014). "We identify two important epigenetic regulators, HDAC1 and DNMT1, which are highly associated with the RGS10 promoter in chemoresistant ovarian cancer cells." (PMID 24475290, 2014). "Together these data suggest that HDAC1 mediated reduction of RGS10 expression blunts the ability of cisplatin to induce cell death in A2780/AD ovarian cancer cells." (PMID 24475290, 2014). "Together, these data indicate that HDAC1 accumulation at RGS10 promoters likely contributes to suppression of RGS10 in chemoresistant ovarian cancer cells." (PMID 24475290, 2014). "In this manner, DNMT1 and HDAC1 synergistically contribute suppression of RGS10 transcription expression as ovarian cancer progresses." (PMID 24475290, 2014). "Ovarian cancer is associated with elevated expression of DNMTs and HDACs and high-level expression of DNMT1 and HDAC1 is prominent in high-grade ovarian tumors." (PMID 24475290, 2014). "Silencing of HDAC1 enhances the sensitivity of ovarian cancer to chemotherapy." (PMID 34691238, 2021). "Similarly, miR-34a has been shown to suppress ovarian cancer cell proliferation and chemoresistance by controlling HDAC1 expression." (PMID 31448054, 2019). "In general, class I HDAC1-3 are upregulated during ovarian cancer progression and correlate with a poor patient survival; while class II HDAC4 overexpression is linked with platinum resistance as well deacetylation of STAT1 in primary ovarian cancer cells isolated from ovarian cancer patients." (PMID 31426393, 2019). "Furthermore, HDAC1 and HDAC3 exhibit aberrant association with OX-40 L and 4-1BBL promoters in chemotherapy-resistant ovarian cancer cells, contributing to suppression of OX-40 L and 4-1BBL." (PMID 30064416, 2018). "Recent reports suggest DNMT1 and HDAC1 expression increases with ovarian cancer stage." (PMID 24475290, 2014).